CTU2 (cytosolic thiouridylase subunit 2)
Diseases named in the same sentence as CTU2 in open-access papers (continued):
Sharing a sentence is not in itself a finding about the gene and the disease.
tumor (2 papers, 2024 to 2025). "In 2024, after completing Phase III clinical trials (NCT03538171), it was approved for treating locally advanced or metastatic breast cancer, highlighting its potential in targeting CTU2-associated tumor progression." (PMID 40375999, 2025). "To go a step further, we performed subcutaneous tumor experiments by huh-7 cells to explore the effects of CTU2 on the tumorigenic ability in vivo." (PMID 40375999, 2025). "Our analysis revealed that, in most tumor types, tumor CTU2 expression is negatively correlated with the infiltration of major immune cell subtypes, such as CD8+ T cells and DC cells." (PMID 40375999, 2025). "Paired Student’s t-test further demonstrated a significant increase in CTU2 expression in multiple tumor tissues compared to adjacent normal tissues." (PMID 40375999, 2025). "To further explore the relationship between tumor CTU2 expression and immune microenvironment infiltration, we analyzed the KIRC single-cell dataset (GSE207493) and the LIHC single-cell dataset (GSE202642)." (PMID 40375999, 2025). "To further investigate the direct role of CTU2 in tumor cell function, we supplemented our analysis with data from the DepMap database." (PMID 40375999, 2025). "Spearman correlation analysis demonstrated a significant positive correlation between CTU2 expression and tumor cell density in specific regions, indicating that CTU2+ cells were primarily clustered in regions populated by malignant cells." (PMID 40375999, 2025). "For instance, molecules associated with antigen presentation, such as those processed and presented by antigen-presenting HLA, were found to be expressed at lower levels in tumor cells with high CTU2 expression." (PMID 40375999, 2025). "Meanwhile, knocking down CTU2 expression in HepG2 cells reduced triglyceride levels in tumor tissues under T0901317 treatment." (PMID 38630355, 2024). "CTU2 IHC staining results showed that tumor sections in shCtrl HepG2 cell-injected groups presented more CTU2 positive staining cells, implying that tumor-forming cells retained the genotype at the time of inoculation." (PMID 38630355, 2024). "T0901317 was able to reduce tumor development, and CTU2 knockdown further reduced T0901317-inhibited tumor growth." (PMID 38630355, 2024). "To determine it, we employed a human tumor xenograft mouse model by injecting HepG2 cells with CTU2 knockdown into nude mice subcutaneously." (PMID 38630355, 2024). "The lipophilic dye Nile red staining showed that T0901317 increased lipid levels in tumor tissues, and CTU2 knockdown inhibited the increased lipid droplets induced by T0901317." (PMID 38630355, 2024). "CTU2 levels were positively correlated to tumor progression (classified as normal and stage 1–4) and poor differentiation (classified as normal and grade 1–4)." (PMID 38630355, 2024). "CTU2 was significantly up-regulated in human HCC tumor compared to normal tissue and tightly associated with tumor development." (PMID 38630355, 2024). "Mechanistically, CTU2 knockdown inhibited tumor cell proliferation, CAF presentation, and tumor vascular generation in vivo." (PMID 38630355, 2024). "Additionally, a significant positive correlation (Spearman r > 0.3; P < 0.05) was detected between CTU2 mRNA expression and copy number variation in the majority of tumor types." (PMID 40375999, 2025). "Therefore, inhibiting CTU2 and T0901317 in combination can suppress the side effects of T0901317 promoting lipogenesis in tumor tissues." (PMID 38630355, 2024). "CTU2 was up-regulated in HCC tumor compared to normal tissue." (PMID 38630355, 2024). "Therefore, inhibition of CTU2 expression synergizes with T0901317 to suppress HCC growth in tumor-bearing mice." (PMID 38630355, 2024). "LXR is a potential anti-tumor target, while its downstream CTU2 promotes cell proliferation in our in vitro study, indicating inhibition of CTU2 expression may enhance antitumorigenic effects of LXR." (PMID 38630355, 2024).
tumor (continued). "Correspondingly, CTU2 knockdown impaired tumor formation in vivo." (PMID 38630355, 2024). "Inhibiting CTU2 expression could synergize with the anti-tumor effects of T0901317." (PMID 38630355, 2024). "Thus, inhibition of CTU2 expression can facilitate the inhibition of tumor growth by LXR ligand." (PMID 38630355, 2024). "CTU2 inhibition may improve the anti-tumor effect while relief the side effect of LXR ligands." (PMID 38630355, 2024). "By comparing tumor burden in each group, we found tumors generated from CTU2 knockdown cells with T0901317 treatment were the smallest, indicating that blocking CTU2 may improve the anti-tumor effect of LXR ligands." (PMID 38630355, 2024). "Hence, inhibition of CTU2 expression in HepG2 cells represses tumor growth in vivo." (PMID 38630355, 2024). "However, inhibiting CTU2 expression reduced TG levels in tumor tissues." (PMID 38630355, 2024). "It is necessary to use CTU2 knockout mice to explore the role of CTU2 in the LXR-mediated lipid metabolism and anti-tumor pathway." (PMID 38630355, 2024). "Reduction of CTU2 expression was related to reduced tumor burden and synergized anti-tumor effect of LXR ligands by inducing tumor cell apoptosis and inhibiting cell proliferation." (PMID 38630355, 2024). "In addition, our study also showed that inhibiting CTU2 expression can suppress tumor cell proliferation, CAF presentation, and promote HCC tumor apoptosis in tumor-bearing mice model." (PMID 38630355, 2024). "CTU2 is also able to facilitate CAF formation and tumor vascular generation in vivo." (PMID 38630355, 2024). "Herein we found inhibition of CTU2 expression decreased VEGFA protein and mRNA expression, which indicated that CTU2 may promote CAF presentation and take part in tumor vascular development." (PMID 38630355, 2024). "Inhibition of CTU2 expression could enhance the anti-tumor effect of LXR ligand in HCC, identifying CTU2 as a promising target for HCC treatment and providing a novel strategy for the application of LXR agonists in anti-tumor effect." (PMID 38630355, 2024).
CTU2 also shares sentences with these, for which no sentence is quoted: renal agenesis (2 papers); brain disorder (1); cervical squamous cell carcinoma (1); clear cell renal cell carcinoma (1); colon adenocarcinoma (1); diffuse large B-cell lymphoma (1); endocervical adenocarcinoma (1); esophageal cancer (1); glioblastoma (1); head and neck squamous cell carcinoma (1); kidney cancer (1); Lissencephaly (1); mastitis (1); non-small cell lung carcinoma (1); pancreatic ductal adenocarcinoma (1); pheochromocytoma (1); renal cell carcinoma (1); sarcoma (1); thymoma (1); tuberous sclerosis (1); uterine cancer (1); uveal melanoma (1).